MED16 (mediator complex subunit 16)
Description:
Component of the Mediator complex, a coactivator involved in the regulated transcription of nearly all RNA polymerase II-dependent genes. Mediator functions as a bridge to convey information from gene-specific regulatory proteins to the basal RNA polymerase II transcription machinery. Mediator is recruited to promoters by direct interactions with regulatory proteins and serves as a scaffold for the assembly of a functional preinitiation complex with RNA polymerase II and the general transcription factors.
Synonyms: Trap95; DRIP92; THRAP5; GGNS
Tractability: Small molecule: a structure with a bound ligand is known. PROTAC: ubiquitination databases record sites on it; its protein half-life has been measured.
Gene: Protein-coding gene on chromosome 19 (867,630 to 893,218, reverse strand). Ensembl gene ENSG00000175221.
Subcellular location: Nucleus
Subcellular location (Human Protein Atlas): Nucleoli
Pathways (Reactome):
Gene expression (Transcription): Generic Transcription Pathway; MLL4 and MLL3 complexes regulate expression of PPARG target genes in adipogenesis and hepatic steatosis
Developmental Biology: Transcriptional regulation of white adipocyte differentiation
Disease: RSV-host interactions
Metabolism: PPARA activates gene expression
Gene Ontology:
Molecular function: nuclear thyroid hormone receptor binding; protein binding; transcription coactivator activity; nuclear vitamin D receptor binding
Biological process: positive regulation of DNA-templated transcription; positive regulation of transcription initiation by RNA polymerase II; positive regulation of transcription elongation by RNA polymerase II; regulation of transcription by RNA polymerase II; RNA polymerase II preinitiation complex assembly; transcription by RNA polymerase II
Cellular component: core mediator complex; mediator complex; membrane; nucleus; nucleoplasm
Genetic constraint (gnomAD): Loss-of-function variants: 80 observed, 73.99 expected, observed/expected ratio (o/e) 1.08, 90% interval 0.9 to 1.3. The synonymous counts are far from expectation, so gnomAD's model fits this gene poorly and the ratio says little. Missense variants: 1,577 observed, 1,177.5 expected, observed/expected ratio (o/e) 1.34, 90% interval 1.28 to 1.4. Synonymous variants: 895 observed, 527.23 expected, observed/expected ratio (o/e) 1.7, 90% interval 1.61 to 1.79.
Homologues: Orthologues: macaque MED16 (98% identical), pig MED16 (88% identical), rat Med16 (87% identical), guinea pig MED16 (87% identical), mouse Med16 (87% identical), dog MED16 (81% identical), tropical clawed frog med16 (76% identical), zebrafish med16 (71% identical), Drosophila melanogaster MED16 (28% identical), chimpanzee MED16 (23% identical).
Diseases named in the same sentence as MED16 in open-access papers:
MED16 is named in the same sentence as 9 diseases in open-access papers, as found by Europe PMC text mining. Sharing a sentence is not in itself a finding about the gene and the disease. The quoted sentences say what the papers report.
breast carcinoma (1 paper, 2022). "We observed that the overexpression of MED16 increases sensitivity to tamoxifen in ER+ breast cancer and vice versa, we also found that knockdown of MED16 promotes autophagy levels." (PMID 36294896, 2022). "In this study, we demonstrated that the mTOR signalling pathway is regulated by the expression level of MED16 in ER+ breast cancer." (PMID 36294896, 2022). "We found that MED16 expression is elevated in breast cancer tissues as well as in cells, and knocking down its expression inhibits the proliferation of ER+ breast cancer cells." (PMID 36294896, 2022). "In summary, we found that MED16 plays an important role in breast cancer progression and treatment, and that its mechanism mainly depends on the activation of mTOR." (PMID 36294896, 2022). "Recent studies have shown that the mediator complex (MED) plays a vital role in tumorigenesis and development, but the role of MED16 (mediator complex subunit 16) in breast cancer (BC) is not clear." (PMID 36294896, 2022).
iron deficiency (1 paper, 2023). "Therefore, the defense and iron deficiency response pathways are related through MED16, because this MED subunit is essential in the SA and JA signaling pathways although additional research is needed to elucidate the extent of this relationship." (PMID 37047208, 2023).
virus infection (1 paper, 2025). "In support of this, we found that both the virus and the aphid vector performed better on med16 mutant Arabidopsis than control plants, indicating that MED16 plays a crucial role in the defense response against aphids and virus infection." (PMID 40170134, 2025). "In Arabidopsis, in the presence of virus infection and aphid feeding, there is a significant level of the putative cleaved MED16 protein detected in the cytosol." (PMID 40170134, 2025). "We also see the same result in Nicotiana benthamiana, where MED16 protein was cleaved in the presence of virus infection at a VLPE site, leading to the removal of the NLS signal leading to the generation of a 21kD fragment of MED16." (PMID 40170134, 2025).
cancer (2 papers, 2022). A tumor composed of atypical neoplastic, often pleomorphic cells that invade other tissues. "To determine the prognostic role of MED16 in BC patients, we analysed the relationship of MED16 expression with individual cancer stages, nodal metastasis status and patient age." (PMID 36294896, 2022). "We also detected the MED16 expression in ER+ BC tissues and normal paracancerous tissues by IHC, and MED16 was mainly expressed in the cytoplasm of cancer cells." (PMID 36294896, 2022). "The close relationship between tumorigenesis among multiple cancer types and numerous mediator complex subunits including MED1, MED12, MED16, and MED19 has been extensively reported." (PMID 35558516, 2022). "Moreover, c-MYC and CCND1 are markers of cancer cell proliferation and cell cycle progression, and western blotting showed that the expression of c-MYC and CCND1 was higher in the MED16 overexpression group." (PMID 36294896, 2022).
infection (2 papers, 2021 to 2024). The state of being infected such as from the introduction of a foreign agent such as serum, vaccine, antigenic substance or organism. "In agreement with their increased susceptibility, med16 and cdk8 showed the largest number of changed metabolite levels at both 24 and 72 h after infection." (PMID 38514763, 2024). "In contrast, med16 was deficient in Glucobrassicin reduction in response to infection." (PMID 38514763, 2024). "Accordingly, induction of JMT, a MYC2 target gene encoding an S-adenosyl-L-methionine:JA carboxyl methyltransferase that catalyzes formation of MEJA from JA, was severely reduced in med16 and med25 due to a combination of elevated levels before, and deficient induction after infection." (PMID 38514763, 2024). "However, previous work targeting Med16 found this knockout is embryonic lethal thus work is underway to develop conditional Med16 knockout animals to specifically test Med16 function in IFNγresponses to infection in vivo." (PMID 34747695, 2021). "Mediator subunits MED8, MED15, MED16, MED18, MED20, MED25 and CDK8 were identified as important for diverse types of infection responses." (PMID 38514763, 2024).
tumor (2 papers, 2018 to 2022). "With the analysis of bioinformatics data and clinical specimens, we revealed an elevated expression of MED16 in luminal subtype tumours." (PMID 36294896, 2022). "The correlations of PIP4K2A with TFDP1 tend to exhibit tumor-specific (i.e., significant in 21/23 tumors but 9/20 normal tissues), while that with MED16 is tend to be in control-specific manner (i.e., significant in 14/23 tumors but 15/20 normal tissues)." (PMID 30697230, 2018).
MED16 also shares sentences with these, for which no sentence is quoted: cervical cancer (1 paper); melanoma (1); Obesity (1).